IL6 (interleukin 6)
Diseases named in the same sentence as IL6 in open-access papers (continued):
Sharing a sentence is not in itself a finding about the gene and the disease.
breast cancer (continued). "In conclusion, this work showed that IL-6 and TNF-α are positively associated with breast cancer in premenopausal women in Latin America." (PMID 35948877, 2022). "Paradoxically, IL-6 had the opposite role in nutrient-poor environments: autophagy resulted in decreased IL-6 secretion, which led to increased breast cancer stem-cell maintenance." (PMID 36295867, 2022). "Immunohistochemical analysis of tumor sections revealed enhanced expression of Ki67 in CM of Act RAW264.7 treated tumor which was inhibited after neutralization of IL-6 suggesting that TAM derived IL-6 induced cell proliferation in breast cancer." (PMID 35300689, 2022). "Overall, modulating IL-6/IL-6Rα interaction shows promising results in all subtypes of breast cancer mediated by IL-6/JAK/STAT3 signaling." (PMID 35371975, 2022). "Based on these results, MIP-1α and IL-6 were then selected as potential candidate targets of sympathetic signaling in breast cancer and proceeded to validate the array by quantifying the expression of these cytokines by ELISA." (PMID 35243294, 2022). "Breast cancer cell-derived vesicular gp130 stimulates bone marrow-derived macrophages (BMDMs) to secrete IL-6 by transferring gp130 into BMDMs which results in phosphorylation of STAT3 causing macrophage polarization and IL-6 secretion." (PMID 36612080, 2022). "It has previously been shown by others that high expression of IL-1A and IL-6 both correlate with poor prognosis for breast cancer patients." (PMID 35260569, 2022). "Using the ORAI1 E106Q pore dead mutant and L273D STIM1 binding-deficient mutant, our study demonstrated that ORAI1 regulation of PTGS2 and IL6 expression in basal breast cancer is dependent on both ORAI1 pore activity and STIM1 binding." (PMID 35682546, 2022). "A study of breast cancer found that secretion of interleukin-6 (IL-6) by tumor cells can recruit and induce an immunosuppressive phenotype in MDSCs." (PMID 36338705, 2022). "Improved therapeutic effects are also associated with increased levels of intratumoural NK cells and IL-6 across multiple breast cancer subtypes." (PMID 36139665, 2022). "Other angiogenic factors such as MMP-2, MMP-9 and IL-6 can also be elevated via the ADRB signaling pathway following stimulation by adrenaline or NA in several breast cancer cell lines." (PMID 35563552, 2022). "Herein, we summarize the biology of the IL-6 signaling pathway, its roles in breast cancer metastasis, and therapeutic advancements in targeting the IL-6/JAK/STAT3 signaling axis." (PMID 35371975, 2022). "In E0771 breast cancer cells, treatment with IL-6 increased PD-L1 MFI as quantified by flow cytometry." (PMID 35775614, 2022). "As an example, breast cancer cells incubated with serum collected immediately after acute exercise – which contained 2.1-fold higher IL-6 than resting serum samples – displayed lower viability in vitro than cancer cells incubated with resting serum." (PMID 35359426, 2022). "For example, several in vitro studies have shown IL-6 to promote breast cancer cells’ EMT transition, migration, and invasion." (PMID 35269622, 2022). "Further, we confirm that TAMs produce high levels of IL-6 and breast cancer cell derived factors induce IL-6 production in activated macrophages via p38-MAPK pathway." (PMID 35300689, 2022). "Senescent mammary fibroblasts stimulate the proliferation of breast cancer cells by secreting IL-6, IL-8, and C-X-C motif chemokine ligand 1 (CXCL1)." (PMID 36291773, 2022). "In turn, CXCL7 induces breast cancer cells and MSCs to secrete a large number of cytokines, including IL-6, IL-8, CXCL6, and CXCL5, which then induce an increase in the population of breast CSCs." (PMID 35837284, 2022). "Our work deciphers the mechanism through which breast cancer cells induce IL-6 expression in tumor activated/educated macrophages." (PMID 35300689, 2022).
breast cancer (continued). "ERα and ERβ are activated after binding to estrogen, form dimers, and bind to target genes such as CCND1, HIF1A, and IL6, which have a role in breast cancer proliferation." (PMID 36106139, 2022). "Core fucosylation of these molecules played important functions in breast cancer cell adhesion to vitronectin and their responsiveness to IL-6 or oncostatin M (OSM) signaling." (PMID 35303925, 2022). "GSEA of public breast cancer patient databases confirmed that IL-6/JAK/STAT3 signaling was significantly correlated with PD-L1 expression." (PMID 35927628, 2022). "Gene set enrichment analysis (GSEA) of public breast cancer patient databases showed that PD-L1 expression was also highly correlated with IL-6/JAK/STAT3 signaling." (PMID 35927628, 2022). "SASPs from the senescent breast cancer cell line MDA-MB-231 and senescent normal epithelial cell line MCF-10A, especially those which highly secrete IL-6 and IL-8, can stimulate the invasion and migration of breast cancer cells in vitro." (PMID 36291773, 2022). "Dysregulated IL-6 promotes a pro-tumorigenic role in the bone microenvironment allowing breast cancer cells to invade the bone." (PMID 35371975, 2022). "High level of IL-6 in breast cancer tissues stimulated Jagged-1 expression to promote cell growth and maintain the aggressive phenotype." (PMID 35924148, 2022). "A previous study has shown that IL-6 expression is correlated with tumor stage, lymph node metastasis, and a poor prognosis in breast cancer." (PMID 36467500, 2022). "Taken together, the IL-6/JAK/STAT3 pathway is a major regulator of breast cancer metastasis through promoting breast cancer cell proliferation, EMT, enriching the breast CSCs, and suppressing apoptosis." (PMID 35371975, 2022). "IL-6 was also correlated with elevated CRP in different kinds of cancers including breast cancer, renal cancer, lung cancer, and colorectal cancer." (PMID 35924148, 2022). "The consequences of inflammatory cytokine, IL-6, on the metastasis of breast cancer process were monitored using this LTB chip." (PMID 35158914, 2022). "Korkaya and colleagues demonstrated that IL-6 was induced in HER2pos breast cancer cells by the HER2 neutralizing antibody Trastuzumab in the setting of PTEN loss, with PTEN inactivation being a known mechanism of resistance to HER2-directed therapies." (PMID 35565421, 2022). "The current review will further discuss the intricate relationship between IL-6, inflammation, and breast cancer." (PMID 35924148, 2022). "The upregulation of the expression of proinflammatory cytokines [including TNF-α, IL-8, and interleukin-6 (IL-6)] and neutrophil survival have been reported to promote protumorigenic (N2) phenotype TANs in a breast cancer model." (PMID 36384979, 2022). "In breast cancer, several studies have shown that patients with breast cancer have increased serum levels of IL-6." (PMID 36429126, 2022). "The study of exosomal miR-9 and miR-181a highlights a key mechanism of MDSC expansion and T-cell immunosuppression driven by IL-6 in breast cancer and targetable pathways to combat breast cancer-mediated immunosuppression." (PMID 36248881, 2022). "Given these important roles in human cancers, multiple components of the IL-6 pathway are promising targets for cancer therapeutics and are currently being evaluated preclinically and clinically for breast cancer." (PMID 35371975, 2022). "IL-6 activates an autocrine JAK1-STAT3 signaling loop that in turn increases STAT3 activation in HER2+ breast cancer cells." (PMID 36291900, 2022). "TAMs promote DNMT1 expression in breast cancer cells via the IL-6-pSTAT3-ZEB1-DNMT1 axis in the TME." (PMID 36273188, 2022). "In advanced metastatic breast cancer cells, overactivated NF-kB promotes chromatin accessibility at the IL-6 promoter region and enhances transcription of the IL-6 gene." (PMID 36163033, 2022).
breast cancer (continued). "High serum IL-6 levels can indicate poor prognosis in breast cancer patients, and has also been correlated with fatigue in other conditions." (PMID 36354718, 2022). "Others have reported IL-6 to promote breast cancer cell proliferation, migration and invasion, and CSCs in breast cancer." (PMID 35371975, 2022). "The role of IL-6 as a promoter of malignancy in breast cancer has been well established in different models and conditions." (PMID 35163731, 2022). "We further demonstrate that TAM derived IL-6 induces CSC enrichment in breast cancer via STAT3 pathway." (PMID 35300689, 2022). "Faecalibacterium prausnitzii inhibits the growth of breast cancer cells by inhibiting the IL-6/STAT3 pathway." (PMID 35889021, 2022). "To summarize, the IL-6/JAK/STAT3 signaling pathway mediates breast cancer progression, metastasis, and therapeutic resistance thus justifying investigations into IL-6/JAK/STAT3 as a targeted therapy for breast cancer patients." (PMID 35371975, 2022). "The shift from cellular dormancy to cell proliferation was also evident through bone TME remodeling by interleukin-6 (IL-6) and the tumor necrosis factor-alpha (TNFα) in metastatic breast cancer cells." (PMID 36430404, 2022). "In breast cancer, the IL-6 pathway is frequently activated, which can promote breast cancer metastasis while simultaneously suppressing the anti-tumor immune response." (PMID 35371975, 2022). "Research has found that IL-6 paracrine loop in breast cancer cells responds to chemotherapeutic drugs, but iron metabolism can break this IL-6 local niche in the tumor microenvironment thus blocking the IL-6 signal pathway to overcome chemoresistance." (PMID 36439106, 2022). "In several types of cancer, such as breast cancer and hepatocellular carcinoma, CAFs can secret IL6 to promote tumor progression." (PMID 35910200, 2022). "This indicates the immune signaling capabilities of obese basal-like breast cancer patients, with IL6 being a key immune response molecule." (PMID 36428692, 2022). "The multicellular crosstalk between human sympathetic neurons, breast cancer cells, and osteoclasts increases cancer cell expression of pro-inflammatory cytokines (IL-6 and MIP-1α)." (PMID 35243294, 2022). "In this study, we showed that breast cancer cells can upregulate OPG in stromal fibroblasts in an IL-6/STAT3-dependent manner." (PMID 36359766, 2022). "Our study illustrates the novel finding that PFKFB4 promotes angiogenesis in breast cancer via IL-6 instead of vascular endothelial growth factor (VEGF) which is a well-established mediator of angiogenesis in cancer." (PMID 34976184, 2022). "The co-culture of ER+ breast cancer cells with obese ASCs activated many pathways such as leptin, IL6, Notch, and jagged canonical Notch ligand 2 (JAG2), which mediated radiation resistance in ER+ breast cancer cells." (PMID 36010901, 2022). "Given that the IL-6/JAK/STAT3 signaling axis promotes metastatic phenotypes of breast cancer, researchers have investigated the role of IL-6/JAK/STAT3 in breast cancer metastasis in vivo to identify key drivers and therapeutic interventions." (PMID 35371975, 2022). "In general, plasma levels of IL-6 and IL-8 positively correlate with the stage of the disease and mortality from breast cancer." (PMID 36286034, 2022). "Further, plasma levels of IL-6 and IL-8 were increased in patients with breast cancer after paclitaxel administration." (PMID 35163066, 2022). "A reduced responsiveness to stimulation of peripheral monocytes observed in TC patients is in line with earlier findings in breast cancer patients, showing an impaired production of IL-1β, IL-6 and TNFα in response to LPS35,36." (PMID 36257966, 2022). "In 1989, a report was published demonstrating for the first time that IL-6 addition to cell culture medium enhanced motility as well as transition from cuboidal to fibroblastoid-like morphology of ER+ breast cancer cells." (PMID 35163731, 2022).
breast cancer (continued). "Serum IL-6 levels in breast cancer patients have been reported to correlate with a poor prognosis and metastasis." (PMID 36010693, 2022). "In 1989, a report was published demonstrating for the first time (emphasis added) that IL-6 addition to cell culture medium enhanced motility as well as the transition from cuboidal to fibroblastoid-like morphology of ER+ breast cancer cells." (PMID 35406728, 2022). "We have shown that AUF1 upregulation in BSFs promotes EMT and stemness in breast cancer cells in an IL-6-dependent manner." (PMID 35821051, 2022). "Treatments targeting the IL-6/JAK/STAT3 pathway have provided benefit for patients with breast cancer by directly inhibiting tumor cell growth and activating anti-tumor immunity." (PMID 35924148, 2022). "Circulating IL-6, an activator of JAK/STAT signaling, is associated with poor prognosis and aromatase inhibitor (AI) resistance in hormone-receptor positive (HR+) breast cancer." (PMID 36369506, 2022). "Our data support a model (graphical abstract) in which mammary tumors repurpose secreted IL-6 and other cytokines to act locally and systemically in reshaping normal Th and myeloid immunity." (PMID 36142210, 2022). "More recently, it has become widely accepted IL-6 mediates an oncogenic role in multiple cancers, including breast cancer, primarily through the activation of STAT3." (PMID 35371975, 2022). "Among these, we identified as the candidate miR-23c target Interleukin 6 Receptor (IL-6R), whose ligand, IL-6, has been shown to play a pivotal role in breast cancer growth and metastasis." (PMID 35406622, 2022). "It was shown that, compared with healthy controls, in the saliva of breast cancer patients, there is an increase in the content of both pro-inflammatory (IL-2, IL-6, and IL-18) and anti-inflammatory cytokines (IL-4 and IL-10)." (PMID 36286034, 2022). "IL-6 was also elevated in many solid tumors including breast cancer, which correlated with poor prognosis and metastasis." (PMID 35924148, 2022). "ASCs/MSCs secrete various growth factors including IGF1 and EGF, and numerous cytokines such as leptin, IL6, adipsin, and TNFα, which stimulate proliferation and survival of breast cancer cells." (PMID 36010901, 2022). "Dual inhibition of H3K9me2 and H3K27me3 inhibited SASP, as indicated by a decrease in SASP components, IL-6 and IL-8, in senescent breast cancer cells." (PMID 35409271, 2022). "Studies have shown that systemic inflammation – characterized by elevated levels of TNF-α, IL-6 and CRP – is associated with an increased risk of breast cancer progression and death." (PMID 36482346, 2022). "So not only do adipocytes and IL6 independently contribute to poor breast cancer prognoses, but their combined effect has been acknowledged as a promoter of angiogenesis." (PMID 35294447, 2022). "The relationship between the level of IL-6 and the early progression of breast cancer has been shown." (PMID 36286034, 2022). "In contrast, local intratumoral autocrine/paracrine IL-6 signaling is crucial for regulating breast cancer cell proliferation, metastasis, and cancer stem cell self-renewal." (PMID 36010693, 2022). "Our findings from HUVEC tube formation studies depicted that TAM derived IL-6 promotes angiogenesis either directly or by inducing angiogenic potential of breast cancer cells via STAT-3 pathway." (PMID 35300689, 2022). "It seems that Th17 cells by creating inflammatory conditions through the secretion of cytokines, including IL-22, IL-17, TNF-α, IL-21, and IL-6, can significantly enhance breast cancer progression." (PMID 35248028, 2022). "Inhibition of autophagy by knocking down ATG7 or beclin 1 in breast cancer stem cells diminishes IL-6 secretion, cell survival as well as mammosphere formation." (PMID 35927755, 2022). "In preclinical model, F. prausnitzii found to suppress the growth of breast cancer through the inhibition of IL-6/STAT3 pathway." (PMID 35167406, 2022).
breast cancer (continued). "So, the blockade of IL-6 inflammatory signaling cascade has been investigated as a potential therapeutic strategy to suppress hepcidin in breast cancer and for anaemic cancer patients." (PMID 35281097, 2022). "This review focuses on emerging studies on the strong linkages of IL-6/IL-6R mediated regulation of inflammation and immunity in cancer, especially in breast cancer." (PMID 35924148, 2022). "We have shown here that recombinant IL-6 treatment enhanced CSC specific marker as well as transcription factor expression in breast cancer cells suggesting that IL-6 alone is able to induce CSC phenotype in breast cancer." (PMID 35300689, 2022). "Specifically, IL-6 is of particular interest due to its increased levels in sera of breast cancer patients when compared to normal sera or tissue of healthy patients." (PMID 35371975, 2022). "In this study, we found that PFKFB4 promotes angiogenesis via IL-6/STAT5A/P-STAT5 signaling in breast cancer." (PMID 34976184, 2022). "IL-6-mediated interactions between pro-adipocytes and breast cancer cells contribute to the progression of breast cancer." (PMID 35701840, 2022). "IL-6 secreted continuously from cancer cells in the bone marrow and promotes osteoclasts differentiation; and Wnt signaling in breast cancer stem cells enables colonization in the bone." (PMID 35159353, 2022). "For example, niclosamide is currently FDA-approved as an anti-parasitic drug, yet treatment exhibited inhibition of IL-6-induced STAT3 activation resulting in suppression of adipocyte-induced EMT in breast cancer cells." (PMID 35371975, 2022). "Breast cancer cells can hijack the IL-6/JAK/STAT3 signaling to evade normal immune responses and further promote tumor growth by activating surrounding microenvironmental cells." (PMID 35371975, 2022). "IL-6 secretion and expression is significantly elevated in therapeutically resistant breast cancer cells when compared to their respective parental lines." (PMID 35371975, 2022). "The mechanisms by which IL-6 mediates crosstalk between the tumor microenvironment and tumor cells continues to be investigated to develop therapeutic targets in breast cancer." (PMID 35371975, 2022). "Recently, toll-like receptor (TLR) 4 was correlated with IL6 expression and poor prognosis in 1 215 breast cancer primaries." (PMID 36224342, 2022). "There are multiple downstream effectors under current mechanistic investigation for their role in mediating IL-6-induced metastatic phenotypes in breast cancer." (PMID 35371975, 2022). "In fact, many breast cancer cell lines produce IL6, which activates STAT3 by signaling through the IL-6 receptor and Jak kinases." (PMID 35327992, 2022). "Compared to the control, IL-6-treated breast cancer cells presented with higher transvascular invasiveness, successfully immobilized and colonized onto the HLEC channel of LTB chips." (PMID 35158914, 2022). "Particularly, the contribution of adipose tissue has called the attention of various authors, since IL-6 serum levels positively correlated with body mass in obese breast cancer patients." (PMID 35163731, 2022). "In prostate cancer, glioma, endometrial cancer, and breast cancer, the IL-6/gp130/STAT3 signaling pathway has been demonstrated to be involved in the regulation of CSC properties such as self-renewal, stemness marker expression, and tumor cell growth." (PMID 35565185, 2022). "For example, tumor secreted IL-6 has been recently reported to enhance metastatic potential through educating monocyte-dendritic progenitors to prime distant organs for breast cancer metastasis." (PMID 35371975, 2022). "PTGS2 and IL6 play important roles in the pathogenesis of breast cancer by promoting tumor growth, invasion, angiogenesis, and apoptosis resistance." (PMID 35682546, 2022). "IL-6 produced by breast cancer cells can induce M2-macrophage polarization by leading to the inhibition of miR-19a-3p expression in TAMs." (PMID 35202089, 2022).